SDHD (succinate dehydrogenase complex subunit D)
Diseases named in the same sentence as SDHD in open-access papers (continued):
Sharing a sentence is not in itself a finding about the gene and the disease.
paraganglioma (continued). "Subsequent arrayCGH of SDHD was pursued and confirmed a deleterious ~2.13 kb deletion encompassing exon 4 of SDHD, resulting in a certain diagnosis of paragangliomas 1 (MIM# 168000)." (PMID 32730690, 2020). "The most frequent germline mutations in pheochromocytoma and paraganglioma are in the SDHB (10.3%) and SDHD (8.9%) genes." (PMID 30456751, 2018). "The prevalence of germline mutations in SDHB, SDHC, SDHD, VHL and MAX in PCC and paraganglioma patients is, respectively, 10%, 1%, 9%, 7%, and 1%." (PMID 29768630, 2018). "In paragangliomas, SDHB alterations were linked to malignancy and SDHD alterations are more frequent in head-and-neck localized tumours." (PMID 28662141, 2017). "SDHD alterations where reported in sporadic and familial paraganglioma, phaeochromocytoma and gastrointestinal stromal tumour (GIST)." (PMID 28662141, 2017). "In 2006, a study comprising a larger number of patients with pheochromocytoma/paraganglioma showed that 33% of the patients carried germline mutations in one of the following genes: VHL, RET, NF1, SDHB, and SDHD." (PMID 24899893, 2014). "Added to that, germline mutations in the mitochondrial succinate dehydrogenase (complex II of the oxidative phosphorylation chain) subunits SDHD, SDHC, and SDHB are a frequent cause of paragangliomas of the head and neck and of phaeochromocytomas." (PMID 21541025, 2011). "In this study of sporadic, SDHD – and PGL2 -linked paragangliomas of the head and neck, we have found very similar gene-expression profiles for all three genetic subgroups." (PMID 19432956, 2009). "We found remarkable similarity in overall gene expression profiles of SDHD -linked, PGL2-linked and sporadic paraganglioma." (PMID 19432956, 2009). "The similarity in gene-expression profiles suggests that PGL2, like SDHD, is involved in the functionality of the SDH complex, and that tumor formation in these subgroups involves the same pathways as in SDH linked paragangliomas." (PMID 19432956, 2009). "In contrast to paraganglioma in SDHB and SDHC-linked families, both located on chromosome 1, in SDHD-linked families and in the recently described SDH5 (SDHAF2) family, only a mutation inherited via the paternal line results in tumorigenesis." (PMID 19956719, 2009). "Familial paragangliomas associated with SDHB and SDHD mutations resemble the carotid body growths that occur as a result of chronic hypoxia exposure in individuals living at high altitudes." (PMID 16103922, 2005). "Germline mutations of SDHD and SDHB are a major cause of the hereditary forms of the tumors paraganglioma and pheochromocytoma." (PMID 16288654, 2005). "Of interest, in a recent study, immunohistochemistry of head and neck paragangliomas with SDHB and SDHD mutations revealed similar suppression of SDHB, which was accompanied by morphologically abnormal mitochondria." (PMID 16103922, 2005). "The syndromic presentation of HNPGLs is associated with mutations in SDHD (paraganglioma syndrome type 1, PGL1), SDHAF2 (PGL2), SDHC (PGL3), SDHB (PGL4), SDHA (PGL5), VHL (von Hippel–Lindau syndrome), HIF-2α (paraganglioma–somatostatinoma–polycythemia), and NF1 (neurofibromatosis type 1 syndrome)." (PMID 39684472, 2024). "Our study’s data and results indicate that not all cases of paragangliomas associated with other neoplasms will exhibit mutations in the SDHD gene." (PMID 39591360, 2024). "Paraganglioma (PGL) is often linked with MEN, and its occurrence is commonly associated with metabolism-related mutation genes, which currently include SDHA, SDHB, SDHC, SDHD, and SDHAF2." (PMID 39591360, 2024). "In the absence of rodent models of paraganglioma with SDHD mutations, the presence of this mutation in dogs, which mirrors the human condition, is particularly significant from a comparative pathology perspective." (PMID 39591360, 2024). "Rare thoracic paragangliomas have been known to be associated with SDHB, SDHD, and VHL genes." (PMID 36138281, 2022).
paraganglioma (continued). "Synaptophysin-positive cells from tumour 44 (a thoracic paraganglioma carrying the SDHD Dutch founder variant p.Asp92Tyr) were noticeably more persistent in cultures with higher lactate levels." (PMID 36178902, 2022). "However, all pathogenic variants identified to date lead exclusively to a parasympathetic head and neck paraganglioma phenotype that is also frequent amongst carriers of SDHC and SDHD missense variants." (PMID 35741787, 2022). "Similarly, paragangliomas, pheochromocytomas and GISTs associated with germline mutation of SDHB, SDHC and SDHD have been previously shown to exhibit CIMP in comparison to tumors caused by mutations in other genes." (PMID 36455002, 2022). "This aggregate result underscores the different tumor spectrum of SDHA-germline variant carriers and Carney Stratakis Syndrome patients, which are known to harbor SDHB, SDHC, or SDHD mutations, and to develop invariably the association of GIST and paraganglioma during their life course." (PMID 35059314, 2021). "Therefore routine surveillance of heterozygous SDHD carriers is suggested for early detection of paragangliomas and phaeochromocytomas and appropriate intervention." (PMID 34012134, 2021). "Although family history was negative, genetic analysis showed a SDHD mutation (c.169_169 + 9delTGTATGTTCT, splice donor defect in exon 2), confirming the diagnosis of hereditary paraganglioma/pheochromocytoma syndrome type 1 (PGL1)." (PMID 33715142, 2021). "Previously reported IL-6 producing paragangliomas did also not show catecholamine excess, in line with our paraganglioma patients who had, like most head neck paragangliomas and SDHD mutation carriers, normal urinary normetanephrine excretion." (PMID 33715142, 2021). "Almost all patients with bilateral/multiple paragangliomas (except a patient with no variants in any of the main susceptibility genes tested) demonstrated pathogenic variants in SDHD." (PMID 33391357, 2020). "In 6 of them, we revealed the existence of pathogenic/likely pathogenic variants of genes encoding for components of the SDH complex (SDHB, SDHD, SDHAF3, and SDHAF4), confirming their high mutation frequency not only in paragangliomas and pheochromocytomas but also in VPGLs as distinct tumor types." (PMID 32948195, 2020). "To further clarify the role of loss of the maternal copy of 11p in relation to loss of the long arm of chromosome 11 in paragangliomas, we used several genetic approaches to determine the allelic status of chromosome 11 in SDHAF2, SDHD, SDHB, and VHL mutant PGLs/PCCs." (PMID 28099933, 2017). "The scarcity of SDHAF2 mutations was reinforced by the failure to document mutations in this gene among 315 patients with paraganglioma and without mutations in the SDHD, SDHC, or SDHB genes." (PMID 24899893, 2014). "The third case appears to be a phenocopy, a sporadic paraganglioma in an SDHD mutation carrier with no immunohistochemical or DNA evidence to support a causal link between the mutation and the tumor." (PMID 25300370, 2014). "The results of both gene- and pathway- based analyses show remarkable similarity in the gene-expression profiles of SDHD -linked, PGL2 -linked and sporadic paragangliomas, suggesting that paraganglioma formation involves the same mechanisms and pathways in these paraganglioma subgroups." (PMID 19432956, 2009). "We have performed a RNA expression microarray study in sporadic, SDHD- and PGL2-linked head and neck paragangliomas in order to identify potential differences in gene expression leading to tumorigenesis in these genetically defined paraganglioma subgroups." (PMID 19432956, 2009). "Characteristically, SDHD mutation is associated with head or neck non-functional paraganglioma, and infrequently, sympathetic paraganglioma or phaeochromocytoma." (PMID 19243216, 2009).
paraganglioma (continued). "Interestingly, Carney-Stratakis syndrome, characterized by germline mutations in SDHB, SDHC, or SDHD, is a hereditary syndrome associated with GIST and paraganglioma, and may also be associated with SDH-mutant RCC." (PMID 40018405, 2025). "Carney-Stratakis syndrome (CSS), a rare condition characterized by paragangliomas and/or pheochromocytomas and gastrointestinal stromal tumors (GIST), is caused by germline heterozygous pathogenic variants in the succinate dehydrogenase subunit genes (SDHB, SDHC, SDHD)." (PMID 40242210, 2025). "In addition to their role in primary mitochondrial disease, heterozygous germline variants in other complex II subunits and assembly factors (including SDHA, SDHB, SDHC, SDHD and SDHAF2) are associated with paragangliomas, phaeochromocytomas and gastrointestinal stromal tumours." (PMID 34012134, 2021). "The lack of differential gene-expression of chromosome 11 genes might indicate that chromosome 11 loss, as demonstrated in SDHD-linked paragangliomas, is an important feature in the formation of paragangliomas regardless of their genetic background." (PMID 19432956, 2009). "The discovery of Succinate Dehydrogenase Subunit D (SDHD) gene in families with Paraganglioma syndrome type 1 (PGL1) in 2000, helped in understanding the molecular mechanism of paraganglioma inheritance." (PMID 38144572, 2023). "Paragangliomas may be hereditary and can be associated with familial paraganglioma, neurofibromatosis type 1, von Hippel-Lindau disease, the Carney triad, multiple endocrine neoplasia type 2, and mutations of the succinate dehydrogenase genes (SDHB, SDHC, and SDHD)." (PMID 17683569, 2007). "It is now recognised that SDHD and SDHB, together with the VHL, RET and NF1 genes, play a major role in the hereditary forms of both pheochromocytoma and paraganglioma." (PMID 16288654, 2005). "In this study, we investigated a woman who presented with pheochromocytoma, paraganglioma, and GIST, fulfilling the criteria for CSS but lacking pathogenic variants or gene deletions in the SDHB, SDHD, or SDHC genes." (PMID 40242210, 2025). "Two-way hierarchical clustering of SDHD-linked, PGL2 -linked and sporadic paragangliomas revealed no clear clusters." (PMID 19432956, 2009). "All evidence indicates that SDHD itself is not imprinted, and we have postulated a role for an imprinted modifier gene on chromosome 11 in SDHD-related paraganglioma." (PMID 19956719, 2009). "In our study, no significant differential expression between sporadic, SDHD and PGL2 -linked paragangliomas was found for these gene sets." (PMID 19432956, 2009). "The H19-SDHD double knockout included H19 as the postulated SDHD-modifier, but did not lead to the development of paragangliomas even after 29 months." (PMID 19956719, 2009). "One SDHD and one SDHB germline variant of uncertain significance were identified in five patients affected by sporadic cases of Cushing’s disease, who did not have any history or sign of pheochromocytoma or paraganglioma." (PMID 35743266, 2022). "More recently, a further hypothesis for the parent-of-origin effects of SDHD expression suggested maternal imprinting at a promoter for a large intergenic ncRNA, designated the name UPGL (untranslated in paraganglioma locus) downstream of SDHD on chromosome 11." (PMID 35938916, 2022). "Furthermore, Chromogranin A does not provide an additive benefit to standard surveillance for predicting the presence of SDHB- or SDHD-related paraganglioma but has a useful negative predictive value when normal in patients with an SDHB mutation." (PMID 34072806, 2021). "Besides, the haplotype around SDHD, conserved in two paragangliomas, is not detected by DASH." (PMID 22567117, 2012).
pheochromocytoma (86 papers, 2004 to 2025). "Researchers reported mutations of SDHD in patients with hereditary pheochromocytomas and hereditary paragangliomas." (PMID 36968495, 2023). "SDHD, identified by differential expression between groups, is currently thought to be associated with familial paraganglioma as well as pheochromocytoma." (PMID 37790931, 2023). "Genomic analysis of familial PGL/pheochromocytoma (PCC) has shown that while mutations of SDHD and SDHC are associated with PGL1 and PGL3, mutations in the large subunit genes SDHB, SDHA and SDHAF2 are associated with PGL4, PGL5 and PGL2." (PMID 35382567, 2022). "Considering hereditary PGLs, 18F-DOPA PET-CT is a sensitive and specific imaging modality for the detection and staging of pheochromocytomas and PGLs and was able to identify PGLs in SDHD mutation carrier in 8/8 cases." (PMID 32098148, 2020). "Heterozygous mutations in SDHB and SDHD have also been linked to pheochromocytoma-paraganglioma syndromes." (PMID 33426505, 2020). "SDHB and SDHD mutations are common in pheochromocytoma/paraganglioma, and SDHA mutations and SDHC promoter hypermethylation are relatively common in GISTs4." (PMID 30971719, 2019). "There is precedence for this model in cancer predisposition: SDHD mutations predispose to phaeochromocytoma almost exclusively when inherited paternally." (PMID 30885698, 2019). "These included melanoma of the parotid gland, breast carcinoma and colorectal carcinoma (same patient), Hodgkins lymphoma, phaeochromocytoma (in a patient with an SDHD mutation) and a pituitary macroprolactinoma." (PMID 29460029, 2018). "Mutations in this gene show a remarkable pattern of parent-of-origin related tumorigenesis, with almost all SDHD-related cases of head and neck paragangliomas and pheochromocytomas attributable to paternally-transmitted mutations." (PMID 25300370, 2014). "Genetic syndromes of pheochromocytoma include multiple endocrine neoplasia type 2 (MEN2A and 2B), neurofibromatosis type 1 (NF1), the pheochromocytoma-paraganglioma syndrome (mutation of the SDHB or SDHD genes), and von Hippel-Lindau syndrome (VHL)." (PMID 23401807, 2013). "Mutations in the SDHB or SDHD genes predispose patients to glomus tumors and occasionally pheochromocytomas." (PMID 23401807, 2013). "Previously, we demonstrated that in SDHD -linked head and neck paragangliomas and phaeochromocytomas this exclusive paternal transmission of the disease is caused by consistent loss of the entire maternal chromosome 11." (PMID 19432956, 2009). "Mutations in SDHB, SDHC and SDHD are also implicated in the formation of phaeochromocytomas, tumors arising in cells derived from the neural crest in the adrenal medulla." (PMID 19432956, 2009). "Our findings link pheochromocytomas with mutations in distinct genes—VHL,SDHB, and SDHD—and suggest that mitochondrial complex II inhibition contributes to development of pheochromocytomas with VHL mutation." (PMID 16103922, 2005). "Mitochondrial complex II is a component of the electron transport chain, and mutations of SDHB or SDHD genes that abrogate the oxidoreductase function of complex II can cause pheochromocytomas." (PMID 16103922, 2005). "Somatic and occult germline SDHD mutations were also detected in patients with apparently sporadic pheochromocytoma (PC)." (PMID 15331017, 2004). "Considering patients affected by pheochromocytomas, mutation in SDHD is found in 2,3% of cases." (PMID 32098148, 2020). "The R22X nonsense SDHD mutation found in hereditary paraganglioma and pheochromocytoma generates a truncated SDHD protein of 21 amino acids (instead of 159), resulting in the loss of complex II electron transfer and enzymatic activities and in the activation of the HIF1α signaling pathway." (PMID 32575796, 2020).
pheochromocytoma (continued). "Complex II mutations, principally affecting SDHB and SDHD subunits, have been associated with various cancers including hereditary paraganglioma and pheochromocytoma (i.e., neuroendocrine tumors of the paraganglionic tissue), gastrointestinal stromal tumors, and renal cell carcinoma." (PMID 32575796, 2020). "These syndromes involve a group of rare autosomal dominant disorders affecting sympathetic and parasympathetic paraganglia, caused by germline mutations of the genes SDHB, SDHC and SDHD, although some of these mutations can also be detected for patients with apparently sporadic pheochromocytomas." (PMID 23360571, 2013). "Mutation in SDHD gene is predominant in head and neck PGLs and has a better prognosis than SDHB-related pheochromocytomas/PGLs." (PMID 39156002, 2024). "Another condition associated with the occurrence of pheochromocytoma is FPGL1, resulting from SDHD (succinate dehydrogenase complex subunit D) gene mutations." (PMID 38802890, 2024). "This case report presents a 10-year-old patient diagnosed with pheochromocytoma/paraganglioma syndrome type 1 (PPGL1), underlined by a novel heterozygous pathogenic variant (c.154_161del, p.ser52Profster14) in the SDHD gene." (PMID 39306716, 2024). "The concurrence of pheochromocytoma and MTC among the familial AMH cases supports a genetic association between familial pheochromocytoma and MTC with RET, SDHD, MAX, and NF1 pathological variants being reported." (PMID 36896586, 2023). "Though this relationship is not specifically related to a germline variant, RET, SDHB, SDHC, SDHD, and SDHAF2 each include a predisposition of developing pheochromocytoma and thus must be considered." (PMID 35685436, 2022). "Elevation of plasma methoxytyramine levels, solitary or together with other plasma metanephrines, has been found in up to 70% of patients with pheochromocytomas arising in the setting of SDHB and SDHD variants." (PMID 35205664, 2022). "Familial CPGLs occur as hereditary paraganglioma/pheochromocytoma (PGL/PCC) syndromes, including PGL1, PGL2, PGL3, PGL4, and PGL5, which are associated with germline mutations in the SDHD, SDHAF2, SDHC, SDHB, and SDHA genes, respectively." (PMID 32971818, 2020). "Germline mutations in succinate dehydrogenase subunit B and D (SDHB and SDHD) are predisposed to hereditary paraganglioma (PGL) and pheochromocytoma (PHEO)." (PMID 30658386, 2019). "In face of the malignant presentation, molecular studies were conducted to screen mutations in five genes related to pheochromocytoma: SDHB, SDHD, SDHC, MAX and VHL." (PMID 29768630, 2018). "Germline mutations in the succinate dehydrogenase (SDHA, SDHB, SDHC, SDHD, SDHAF2) or Von Hippel-Lindau (VHL) genes cause hereditary paraganglioma/pheochromocytoma." (PMID 28099933, 2017). "On the other hand, SDH mutations cause intra-adrenal tumours less commonly; 25% of SDHB-related tumours are phaeochromocytomas while the frequency of intra-adrenal tumours in SDHD, SDHA and SDHC are even lower." (PMID 29166454, 2017). "To better characterize the function of PNMT in PCC/PGL, we analyzed a large (125 samples) public PCC/PGL microarray expression profile dataset (GSE19987) with a variety of mutations in pheochromocytoma susceptibility genes such as RET, VHL, SDHB and SDHD." (PMID 27007161, 2016). "Somatic mutations in sporadic pheochromocytoma/paraganglioma has been identified in VHL, RET, SDHB, and SDHD but their frequency was reported to be low." (PMID 26347711, 2015). "Mutations of SDHD, the first protein of intermediary metabolism shown to be involved in tumorigenesis, lead to the human tumors paraganglioma (PGL) and pheochromocytoma (PC)." (PMID 19956719, 2009). "In patients with familial pheochromocytoma screening for gene mutations in the RET, VHL, SDHB and SDHD gene is recommended since different familial syndromes can be revealed." (PMID 17922902, 2007).